LCN1 (lipocalin 1)
Description:
Could play a role in taste reception. Could be necessary for the concentration and delivery of sapid molecules in the gustatory system. Can bind various ligands, with chemical structures ranging from lipids and retinoids to the macrocyclic antibiotic rifampicin and even to microbial siderophores. Exhibits an extremely wide ligand pocket.
Synonyms: Tlc; TP; VEGP; PMFA; MGC71975
Tractability: Small molecule: a structure with a bound ligand is known; it has a high-quality binding pocket. Antibody: its Gene Ontology location is reachable by antibodies, with high confidence; UniProt places it where antibodies can reach, with medium confidence; UniProt predicts a signal peptide or a membrane-spanning region.
Gene: Protein-coding gene on chromosome 9 (135,521,438 to 135,526,540, forward strand). Ensembl gene ENSG00000160349.
Subcellular location: Secreted
Pathways (Reactome):
Transport of small molecules: Transport of fatty acids
Gene Ontology:
Molecular function: chloride ion binding; protein binding; signaling receptor binding; zinc ion binding; cysteine-type endopeptidase inhibitor activity; small molecule binding
Biological process: proteolysis
Cellular component: extracellular region
Genetic constraint (gnomAD): Loss-of-function variants: 25 observed, 21.47 expected, observed/expected ratio (o/e) 1.16, 90% interval 0.85 to 1.62. The upper end of that interval is the gene's LOEUF score, 1.62, which puts it in group 6 of 6, group 1 being the genes least tolerant of losing a copy. Missense variants: 219 observed, 228.19 expected, observed/expected ratio (o/e) 0.96, 90% interval 0.86 to 1.07. Synonymous variants: 85 observed, 95.39 expected, observed/expected ratio (o/e) 0.89, 90% interval 0.75 to 1.07.
Homologues: Orthologues: chimpanzee LCN1 (98% identical), macaque LCN1 (91% identical), dog OBP2B (57% identical). Paralogues in human: OBP2B (45% identical), OBP2A (44% identical), LCN15 (24% identical), LCN9 (21% identical), LCN12 (20% identical), LCN6 (18% identical), PAEP (18% identical), PTGDS (18% identical), LCN10 (17% identical), LCN2 (15% identical), LCN8 (14% identical), LCNL1 (11% identical).
Diseases named in the same sentence as LCN1 in open-access papers:
LCN1 is named in the same sentence as 29 diseases in open-access papers, as found by Europe PMC text mining. Sharing a sentence is not in itself a finding about the gene and the disease. The quoted sentences say what the papers report.
diabetic retinopathy (4 papers, 2020 to 2024). "In a recent study, LCN1 in tears demonstrated its potential as a biomarker in screening diabetic retinopathy, which brings expectations for LCN1 to become a biomarker of AMD." (PMID 38087257, 2023). "Regarding the inflammatory process, in tears, lactotransferrin, lipocalin 1 (LCN-1), lysozyme C, lipophilin A, lacritin, and immunoglobulin lambda chain levels increased in patients with diabetic retinopathy." (PMID 34575451, 2021). "The level of a diabetic retinopathy (DR) biomarker, lipocalin-1 (LCN-1), was measured in 1 μL of a human tear sample and used in testing the practicability of the proposed device." (PMID 32977557, 2020). "It has also been suggested optoelectronic and optoelectrokinetic bead-based immunosensors for lipocalin-1 detection and Au-NP-doped diffusometric immunosensors for TNF-αdetection have been developed to diagnose diabetic retinopathy in tears." (PMID 39867928, 2024).
dry eye (4 papers, 2020 to 2025). "Specifically, LACRT is secreted from the submandibular salivary gland and has been associated with inflammatory disorders such as dry eyes, while LCN‐1 is secreted from the lingual von Ebner's glands." (PMID 39895030, 2025). "Lipocalin-1 was a candidate as a biomarker of dry eye syndrome." (PMID 36539822, 2022). "Lipocalin-1, a major component of normal tears, along with lysozyme C and lactotransferrin, both antimicrobial proteins, are produced by the lacrimal gland and are also downregulated in tears from dry eye patients." (PMID 33372592, 2020). "Based on our study, attention should be paid to genes such as LCN1, LTF and SCGB2A1, which had lower expression levels in pterygium, to determine whether they are directly involved in the development of pterygium and dry eye." (PMID 32411530, 2020).
breast carcinoma (3 papers, 2017 to 2022). "The expression of LCN1 was found to be significantly increased in breast cancer tissues compared with adjacent normal tissues, possibly resulting from more neoantigens in cancer patients and therefore more immune infiltration." (PMID 32411530, 2020). "However, it remains to be investigated whether LCN1 might exert tumor-promoting functions like its family member LCN2 known to induce epithelial to mesenchymal transition and to promote breast cancer invasion in an ERα-dependent manner." (PMID 28482871, 2017).
keratoconus (2 papers, 2022). A degenerative, structural disorder of the eye, characterized by a cone-shaped protrusion of the cornea. "Namely, there is an apparent overlap of differentially expressed prolactin-induced protein (PIP), lipocalin-1, lysozyme C, zinc alpha 2-glycoprotein and serum albumin between keratoconus and ocular allergy sufferers." (PMID 35205178, 2022).
allergic asthma (1 paper, 2024). A asthma with a basis in a pathological type I hypersensitivity reaction. "Strong suppression of inflammation in allergic asthma has been achieved in phase I/II studies using interleukin-4 receptor subunit alpha (IL-4Ra) antagonists with lipocalin-1 nanocarriers." (PMID 39204164, 2024).
Alzheimer disease (1 paper, 2023). A progressive, neurodegenerative disease characterized by loss of function and death of nerve cells in several areas of the brain leading to loss of cognitive function such as memory and language. "A combination of four tear proteins—lipocalin 1, dermcidin, lysozyme C, and lacritin—was shown to have 81% sensitivity and 77% specificity for Alzheimer’s disease." (PMID 36983883, 2023). "Furthermore, the tear fluid of Alzheimer’s disease patients included considerably lower amounts of lysozyme, lipocalin 1, and lacritin, as well as higher levels of dermcidin." (PMID 36983883, 2023).
asthma (1 paper, 2023). "In contrast, increased LCN1 expression in asthma has been shown to activate the NF‐κB pathway and causes inflammation." (PMID 38018577, 2023).
atopic dermatitis (1 paper, 2025). "Additionally, both Can f 1 and Fel d 7 (cat lipocalin) share 57.7% sequence identity with human lipocalin-1 (encoded by the LCN1 gene), and the presence of sIgE to these allergens could serve as a marker of the severity of atopic dermatitis (AD)." (PMID 40739451, 2025).
cholangiocarcinoma (1 paper, 2021). A carcinoma that arises from the intrahepatic biliary tree (intrahepatic cholangiocarcinoma) or from the junction, or adjacent to the junction, of the right and left hepatic ducts (hilar cholangiocarcinoma). "As another gene targeting tretinoin, the Lipocalin 1 (LCN1) was found highly expressed in cholangiocarcinoma and its overexpression indicated poor survival outcome; however, its involvement in tumor immunosuppression has not yet been explored." (PMID 34422810, 2021).
intra-amniotic infection (1 paper, 2015). "We revealed and verified significant change in levels of lipocalin-1, glycodelin, and nicotinamide phosphoribosyltransferase due to the presence of microbial invasion of the amniotic cavity and histological chorioamnionitis." (PMID 26120581, 2015).
lung disease (1 paper, 2024). "The cysteine protease inhibitors cystatin B, cystatin SA and lipocalin-1 are decreased in frequent exacerbators, but their specific role in lung disease has not been characterised." (PMID 38135443, 2024).
oligoasthenoteratozoospermia (1 paper, 2024). A form of male infertility that is characterized by a combination of low number or oligozoospermia, poor motility or asthenozoospermia, and abnormal shape or teratozoospermia of sperms. "Key proteins associated with sperm function, such as NPC intracellular cholesterol transporter 2 (NPC2), galectin-3-binding protein (LGALS3BP), lipocalin-1 (LCN1), and prolactin-inducible protein (PIP), show reduced expression in oligoasthenoteratozoospermia (OAT)." (PMID 39685846, 2024).
oligodendroglioma (1 paper, 2021). A well-differentiated (WHO grade II), diffusely infiltrating neuroglial tumor, typically located in the cerebral hemispheres. "The finding of a neural transcriptomic signature for LCN1 is consistent with prior reports of synaptic enrichment among low-grade tumours and oligodendrogliomas, which each utilized sample sizes larger than implemented here." (PMID 34917940, 2021).
periodontitis (1 paper, 2025). An acute or chronic inflammatory process that affects the tissues that surround and support the teeth. "Lipocalin-1 was the most underexpressed saliva protein with a nearly three times lower expression in periodontitis." (PMID 40384977, 2025).
pterygium (1 paper, 2020). A wedge-shaped fibrovascular lesion arising from the bulbar conjunctiva and extending to the cornea. "From the results of RNA-Seq, LCN1, LTF, SCGB2A1, HBA1 (hemoglobin subunit alpha 1) and HBA2 (hemoglobin subunit alpha 2) ranked as the top five DEGs in the comparison between pterygium and normal tissues." (PMID 32411530, 2020). "The mRNA expressions of SCGB2A1, LTF and LCN1 were significantly decreased in pterygium tissues compared with normal control tissues, while the mRNA levels of HBA1 and HBA2 were higher in the pterygium tissues than in the control tissues." (PMID 32411530, 2020).
thymoma (1 paper, 2017). A neoplasm arising from the epithelial cells of the thymus. "The characteristic members of this group are GIF, CYP2A7, LCN1, as well as GAD2, the expression of which followed AIRE’s expression pattern in thymomas, and conceivably CT-As, for which AIRE-dependency in human thymus remains unknown." (PMID 28861084, 2017).
tumor (7 papers, 2017 to 2022). "We measured the expression of six different Zn-binding proteins in tissue microarrays (TMAs) from OPSCC patients by IHC in matched tumor and normal tissue, including: Lipocalin-1 (n = 63), AZGP1 (n = 68), albumin (n = 26), S100A7 (n = 53), S100A7 (n = 53), S100A8 (n = 51) and S100A9 (n = 50)." (PMID 31740720, 2019). "To determine whether these enrichments were exclusively driven by LCN1’s association with pathology, we performed a follow-up GSEA for LCN1 where tumour grade and IDH/1p19q status were included as covariates, and found that LCN1 remained enriched for synaptic signalling ontologies." (PMID 34917940, 2021). "Interestingly, the effect of LCN1 was no longer significant after pathology variables (i.e. tumour grade and IDH/1p19q-status) were included in the model, suggesting that the association between LCN group and tumour molecular genetics drove the differences in survival outcome." (PMID 34917940, 2021).
infection (4 papers, 2013 to 2023). The state of being infected such as from the introduction of a foreign agent such as serum, vaccine, antigenic substance or organism. "In addition to α-2M and lipocalin-1, we identified several additional proteins that may protect the uterus against infection and tissue damage associated with implantation." (PMID 28405395, 2017). "However, as we now show that human neutrophils express Lcn-1, it is possible that Lcn-1 also has a protective role during active infection." (PMID 23853581, 2013). "In addition to showing inhibition of siderophore biosynthesis, the current study demonstrates that exogenous lipocalin-1 impairs fungal growth in the presence of human neutrophils and during infection." (PMID 23853581, 2013). "Taken together, these observations suggest that lipocalin-1 may work alongside α2M to protect the uterine environment against infections, and its lipid-binding may involve sequestration of toxic lipid peroxidation products created under condition of oxidative stress." (PMID 28405395, 2017). "Although LCN1 concentration increases during inflammation and/or infection, the impact of this expression has not been interrogated for any pathogen and these investigations are hampered by the lack of LCN1 expression in mice." (PMID 36054235, 2022).
LCN1 also shares sentences with these, for which no sentence is quoted: cancer (3 papers); primary Sjögren’s syndrome (2); Allergy (1); dental caries (1); hepatocellular carcinoma (1); macular edema (1); nasopharyngeal carcinoma (1); non-proliferative diabetic retinopathy (1); proliferative diabetic retinopathy (1); steatosis (1); systemic lupus erythematosus (1).